SPHK1 (sphingosine kinase 1)
Diseases named in the same sentence as SPHK1 in open-access papers (continued):
Sharing a sentence is not in itself a finding about the gene and the disease.
melanoma (continued). "Finally, we recently discovered that melanoma patients with low SphK1 expression had significantly longer progression-free survival and overall survival than those with high SphK1 expression and patients with high SphK1 expression mostly failed to respond to anti-PD-1 therapy." (PMID 32858889, 2020). "In order to evaluate whether SPHK1 expression was related to the therapeutic outcome in advanced melanoma patients receiving anti-PD-1 therapy, we analyzed SPHK1 messenger RNA (mRNA) expression in tumor biopsies by in situ hybridization using the RNAscope technology." (PMID 31974367, 2020). "Indeed, it has been discovered that patients with low SphK1 expression in melanoma cells had significantly longer progression-free survival and overall survival than those with high SphK1 expression and patients with high SphK1 expression mostly failed to respond to anti-PD-1 therapy." (PMID 33121001, 2020). "Thus, Sphk1 is a promising target for improving anti-melanoma immune response." (PMID 33121001, 2020). "Finally, SphK1 inhibition by the sphingosine-competitive inhibitor PF-543 or Sphk1 downregulation by shRNA enhanced the efficacy of immune checkpoint blockade therapies in murine melanoma models, reducing Treg induction and infiltration, respectively." (PMID 33121001, 2020). "Thus, expression of SphK1 in dermal fibroblasts enhanced tumor growth in a model of melanoma." (PMID 27800303, 2016). "It has been shown that the decreased expression of SphK1 improves the efficacy of immune checkpoint inhibitors such as anti-CTLA-4 and anti-PD-1 therapy in melanoma, breast, and colon cancer mouse models." (PMID 39940821, 2025). "SPHK1 and MTA3 hold the potential to function as novel biomarkers to predict melanoma patient outcomes upon anti-PD-1 mAb blockade therapy." (PMID 36050478, 2022). "Importantly, the results showed that compared with IgG2a treatments, PD-1 blockade therapies significantly reversed SPHK1- or MTA3-associated immune dysfunctions and enhanced the immune response against tumor cells, as reflected by the frequencies of CD8+ and GZMB+CD8+ T lymphocytes in melanoma." (PMID 36050478, 2022). "Significantly, we identified SPHK1 and MTA3 as biological markers for predicting the efficacy of anti-PD-1 mAb therapy in melanoma patients." (PMID 36050478, 2022). "First, SphK1 expression and activity are induced by ERK1/2 and AKT in numerous mammalian cells, including melanoma cells." (PMID 32858889, 2020). "Augmented endocytosis of E-cadherin has also been reported and autophagy-induced degradation, due to overexpression of SIRT1, SPHK1, or PHF8 have been described in melanoma and hepatocarcinoma." (PMID 32714931, 2020). "Sphk1 and Sphk2 maintained a reciprocal regulation in PKCδ silenced B16F10 melanoma cells in a time dependent manner, which was found to be correlated with the activity assay of sphingosine kinases." (PMID 30701020, 2018). "Certainly, we established that intracellular S1P generated by SphK1 was a required cofactor for TRAF2 E3 ubiquitin ligase activity, linking TNF signaling to NF-κB activation in melanoma cells." (PMID 27800303, 2016). "sphingosine kinase 1 (SK1) and S1P are key players of TNF signaling in melanoma cells." (PMID 39136013, 2024). "Furthermore, we delineated the expression of SPHK1, MTA3, c-Myc, and PD-L1 and tumor-infiltrating immune cell profiles in melanoma biopsies from a total of nineteen patients regularly receiving PD-1 blockade therapies (toripalimab)." (PMID 36050478, 2022). "Consistent with previous analyses, we found that inhibition of SPHK1 activity significantly diminished the levels of CD4+CD25+FoxP3+ regulatory T cells (Tregs) and Gr-1+CD11b+ myeloid-derived suppressor cells (MDSCs) in melanoma." (PMID 36050478, 2022).
melanoma (continued). "The goal of this study was to assess the role of SPHK1 in antitumor immunity, reveal a novel molecular mechanism regarding the regulation of PD-L1 via MTA3, and further investigate the clinical significance of the SPHK1-MTA3 axis in immunotherapy in melanoma." (PMID 36050478, 2022). "The mRNA levels of ASAH1 (acid ceramidase, a ceramide-hydrolyzing enzyme), were higher in melanoma than in normal tissue, while SPHK1 mRNA (encoding sphingosine kinase 1) was not different between groups." (PMID 36077841, 2022). "A recent study showed that inhibition of sphingosine kinase-1 (SK1) resulted in decreased Tregs trafficking to the tumor and consequently enhanced response to ICI in the murine model of various cancers including melanoma." (PMID 32517213, 2020). "SphK1 activity is induced by ERK1/2 and SphK1 knockdown impaired anchorage-dependent and -independent growth of different human melanoma cells in vitro, as well as B16F10 and Yumm1.7 murine melanoma cell growth in vivo." (PMID 33121001, 2020). "Accordingly, the SphK1 inhibitor SKI-I, which increases the intracellular ceramide levels and decreases S1P levels in melanoma cells, resulted in a cell cycle arrest between G2/M and S phases as well as increased apoptotic cell death, caspase-3 activation and nuclear accumulation of cleaved PARP." (PMID 32858889, 2020). "The fact that E-cadherin may be downregulated through the activation of autophagy has been already demonstrated on melanoma and hepatoma cells in which SIRT1 and SPHK1, respectively, regulate this process." (PMID 32714931, 2020). "Moreover, SphK1 inhibition, using either FTY720 or SKI-I in several melanoma cell lines, increased their sensitivity to the BRAF inhibitor vemurafenib." (PMID 33121001, 2020). "As PD-1 on CD8+ T-cell subsets is a novel identified marker in predicting the response to anti-PD-1 immunotherapies, these data suggest that SPHK1 and MTA3 may serve as potential biomarkers for the prognosis of melanoma and the efficacy of PD-1 mAb blockade therapies." (PMID 36050478, 2022). "Taken together, our results indicated that SPHK1 might play a pivotal role in the TME and that an SPHK1 inhibitor has the potential to facilitate an antitumor response by downregulating PD-L1 on melanoma cells and thereby reversing the dysfunctional status of tumor-infiltrating CTLs." (PMID 36050478, 2022). "Our findings revealed a novel role for SPHK1 in tumor evasion mediated by regulating the MTA3-PD-L1 axis, identified SPHK1 and MTA3 as predictors for assessing the efficacy of PD-1 mAb treatment, and provided a therapeutic possibility for the treatment of melanoma patients." (PMID 36050478, 2022). "Importantly, the SphK1/S1P pathway could also modulate MITF levels, probably by acting on signaling pathways known to regulate its expression in melanoma cells." (PMID 33121001, 2020). "Indeed, SphK1 inhibition by the immunomodulator FTY720, which is also a functional antagonist of S1P receptors, downregulated the PI3K/AKT/mTOR signaling pathways and EGFR expression in SK-Mel-28 and A375 human melanoma cells, resulting in an increased sensitivity to cisplatin." (PMID 33121001, 2020). "Here, the authors show a significant negative correlation between sphingosine kinase-1 (SK1) expression and survival for ICI-treated melanoma patients, and further show that targeting SK1 improves response to ICI in mouse cancer models." (PMID 31974367, 2020).
colorectal cancer (33 papers, 2014 to 2025). A primary or metastatic malignant neoplasm that affects the colon or rectum. "Previous studies have demonstrated that Sphk1 expression levels are increased in the colons of patients with ulcerative colitis (UC) or colorectal cancers, and the increased expression of Sphk1 and S1P is associated with poor outcomes." (PMID 28991193, 2017). "Mechanistic studies revealed that PRSS8 inhibited Sphk1/S1P/Stat3/Akt signaling pathway, in terms of inverse association between PRSS8 and Sphk1 in human colorectal cancers and in Sphk1-/− mice." (PMID 27050145, 2016). "A recent study has reported that persistent activation of Stat3 by the Sphk1/S1P signaling pathway is observed in chronic intestinal inflammation and colitis-associated colorectal cancer." (PMID 27050145, 2016). "Furthermore, SPHK-1-positive expression is significantly associated with VM and poor survival in colorectal cancer." (PMID 36139362, 2022). "In addition, Sphk1/S1P signaling is associated with cancer metastasis, chemoresistance, and survival of patients with colorectal cancers and neuroblastoma." (PMID 28991193, 2017). "The selective SphK1 inhibitor PF-543 exhibits cytotoxic effects on both colorectal cancer cells and head and neck squamous cell carcinoma (SCC)." (PMID 40006080, 2025). "The positive SPHK1 expression in advanced colorectal cancer (stages III and IV) was higher than in less advanced tumors." (PMID 37108361, 2023). "The expression density of SPHK1 in primary colorectal cancer tissues was higher compared with normal colonic mucosa tissues, whereas the expression of E-cadherin was lower." (PMID 37108361, 2023). "PF-543, the known SphK1 inhibitor, activated programmed necrosis pathway in human colorectal cancer (CRC) cells." (PMID 35296639, 2022). "We recently identified the sphingosine kinases (SphK1/2) as key intracellular regulators of immunogenic cell death (ICD) in colorectal cancer (CRC) cells." (PMID 36358599, 2022). "For example, SK1-I and PF-543, two potent SphK1 inhibitors, suppress the growth of glioblastoma and colorectal cancer cells in xerograph mouse model, respectively." (PMID 35822041, 2021). "For instance, TRIM14 accelerated the migration and invasion abilities of colorectal cancer cells through regulating SPHK1/STAT3 signaling." (PMID 33892646, 2021). "(2019) suggest that POTEE paralog promotes colorectal cancer by upregulating the SPHK1/p65 signaling pathway." (PMID 34788504, 2021). "Like SphK1, SphK2 has been found to be overexpressed in various cancer types such as non-small-cell lung cancer and colorectal cancer." (PMID 34069611, 2021). "Overexpression or knockout of SphK1 has been shown to enhance or inhibit tumorigenesis, respectively, as exampled in a murine model of colorectal cancer." (PMID 29643998, 2018). "This review summarizes the features of Sphk1/S1P signaling and their functions in colorectal cancer cell growth, tumorigenesis, and metastasis, inhibitors of Sphk1/S1P signaling, as well as the possible underlying mechanisms." (PMID 28991193, 2017). "This review summarizes the features of Sphk1/S1P signaling and their functions in colorectal cancer cell growth, tumorigenesis, and metastasis, as well as the possible underlying mechanisms." (PMID 28991193, 2017). "In vitro, knockdown of Sphk1 in colorectal cancer cells results in inhibition of cancer cell proliferation, migration, and invasion, which is through increasing E-cadherin expression and decreasing vimentin expression." (PMID 28991193, 2017). "It is known that Sphk1 is overexpressed in colorectal cancer tissues and cell lines, and the upregulation of Sphk1 is well correlated poor survival, mainly due to metastasis to lymph node, liver, and other organs." (PMID 28991193, 2017).
colorectal cancer (continued). "Mechanistically, PRSS8 negatively correlated with Sphk1 in both a Sphk1 knockout mouse model and human colorectal cancers." (PMID 28991193, 2017). "Recent studies have demonstrated that the Sphk1/S1P axis causes the activation of NF-kB and transcription factor STAT3 and connects chronic inflammation and colitis-associated colorectal cancer, providing a novel mechanism of colitis malignant transformation." (PMID 27050145, 2016). "The results generated from these experiments strongly suggested that PRSS8 is a tumor suppressor in colorectal cancer, which is through inhibiting Sphk1/S1P/Stat3 signaling pathways." (PMID 27050145, 2016). "Moreover, patients with SPHK1-positive colorectal cancer cells had a significantly lower survival rate compared with patients with SPHK1-negative cancer." (PMID 37108361, 2023). "Down-regulation of SphK1 activity by pharmacological inhibitor N,N-dimethylsphingosine (DMS) or siRNA restored sensitivity to cetuximab in colorectal cancer cells with intrinsic or acquired resistance to cetuximab, whereas over-expression of SphK1 precluded cetuximab-induced apoptosis." (PMID 32456134, 2020). "Importantly, down-regulation of both S1P-producing enzymes SphK1 and SphK2 by siRNA reduced the formation of focal adhesions in primary colorectal cancer cells, which was accompanied by suppression of FAK activity." (PMID 32456134, 2020). "The role of SphK1 in resistance mechanisms to cetuximab was additionally corroborated by the finding that SphK1 expression significantly correlates with response to cetuximab in colorectal cancer patients." (PMID 32456134, 2020). "Increased expression levels of Sphk1 and S1P in colorectal cancers and in the plasma were also observed in mouse models with the treatment of carcinogen azoxymethane (AOM) followed by chronic colitis induced by oral administration of dextran sodium sulfate (DSS)." (PMID 28991193, 2017). "MiRNA-101 inhibited colorectal cancer cell proliferation by targeting Sphk1." (PMID 28991193, 2017). "Moreover, Sphk1 is a direct target of miR-659-3p in colorectal cancer cells, and it is negatively regulated by miR-659-3p." (PMID 28991193, 2017). "Interestingly, in normal colonic mucosa, PRSS8 expression was higher and Sphk1 was lower, but, in colorectal cancer tissues, PRSS8 expression was decreased and Sphk1 expression was increased, showing an inverse correlation." (PMID 27050145, 2016). "The decrease of PRSS8 during carcinogenesis could be resulted from promoter hypermethylation, and the increase of Sphk1 could be activated by upstream signaling (e.g. inflammatory signaling) during colorectal cancer initiation and progression." (PMID 27050145, 2016). "Moreover, the expression of Sphk1 was significantly correlated with the expression of FAK or p-FAK, and the co-expression of Sphk1, FAK, and p-FAK was significantly associated with colorectal cancer histopathological grades, Dukes’ stages, lymph node metastasis, and distant metastasis." (PMID 28991193, 2017). "Furthermore, previous studies have found that SPHK1 overexpression is a prognostic biomarker for the survival of patients with glioblastoma, head and neck cancer, salivary duct cancer, esophageal cancer, gastric cancer, and colorectal cancer." (PMID 26311741, 2015). "A sphingolipid metabolite regulator, sphingosine kinase 1 (SPHK1), plays a critical role in the development of colorectal cancer (CRC)." (PMID 38135696, 2024). "Regarding colorectal cancer cells, resistance to cetuximab-induced cell death in various CRC cell lines was determined by the activity of sphingosine kinase 1 (SPHK1) and the S1P/Cer ratio." (PMID 37446046, 2023). "High expression of SphK1 correlates with CRC progression, aggressiveness, distant metastasis and poor overall survival of the patients suffering from colorectal carcinoma." (PMID 32456134, 2020).
colorectal cancer (continued). "The crosstalk of IL-6/STAT3 and SphK1/S1P/S1PR pathways has been suggested to play an essential role in the progression of inflammation related tumors, such as colorectal cancer." (PMID 29643998, 2018). "Interestingly, the HT-29 colorectal cancer cell line, which expresses the highest SphK1 levels, was more vulnerable to PF-543 treatment than DLD-1, which has the lowest SphK1 expression." (PMID 40006080, 2025). "Notably, the combination of SPHK1 inhibition and TRAIL dramatically reduced the expression of a range of intracellular and cell surface CSC markers in colorectal cancer tumorspheres." (PMID 41253780, 2025). "We have recently demonstrated that the synthetic cannabinoid (±) 5-epi CP 55,940 (5-epi) stimulates the accumulation of ceramide (Cer), and that inhibition of sphingosine kinase 1 (SphK1) enhances Cer accumulation and ICD-induction in human colorectal cancer (CRC) cell lines." (PMID 39682160, 2024). "The aim of our study was to investigate how the modulation of sphingolipid metabolism through the silencing of the genes involved in the formation (SPHK1) and degradation (SGPL1) of sphingosine-1-phosphate would affect the sphingolipid profile and apoptosis of HCT-116 human colorectal cancer cells." (PMID 37108361, 2023). "SphK1 coupled to ERK1/2 signaling is able to regulate autophagy via mTOR downregulation and consequent up-regulation of the ULK1 (Unc-51 like autophagy activating kinase) activity, as shown in HT29 colorectal carcinoma cell line." (PMID 32456134, 2020). "Results showed that increased SPHK1 mRNA level could predict poorer overall survival than those patients with relatively low SPHK1 expression in GSE17538 dataset with 178 CRC samples and in TCGA database with 362 colorectal cancer patients involved." (PMID 31723122, 2019). "Although increasing studies have reported the important roles of Sphk1/S1P signaling in colorectal cancers, there is a lack of systemic summarization." (PMID 28991193, 2017). "We found that PRSS8 inhibited Sphk1/S1P/Stat3 signaling, in terms of negative correlation of PRSS8 and Sphk1 in vitro, in Sphk1 mouse model and in human colorectal cancers." (PMID 27050145, 2016). "In conclusion, we have identified PRSS8 as a tumor suppressor in colorectal cancer formation and progression, and PRSS8 might be one of the key elements that suppress Sphk1/S1p/Stat3/Akt inflammatory signaling during colorectal carcinogenesis." (PMID 27050145, 2016). "More recently, we also demonstrated that cross-talks between Sphingosine Kinase 1 (SphK1) and EGFR-dependent signaling pathways could mediate resistance to cetuximab in colorectal cancers." (PMID 23992330, 2014). "Altogether, our findings suggested a POTEE/SPHK1/p65 signaling axis could promote colorectal tumorigenesis and POTEE might potentially serve as a novel biomarker for the diagnosis and an intervention of colorectal cancer." (PMID 31723122, 2019). "Furthermore, the STAT3-S1PR pathway that has been reported previously to mediate the effect of SphK1 on colorectal cancers was not altered by SphK1 deletion in liver cancer." (PMID 29643998, 2018). "ICAM-1 and VCAM-1 are considered the key players in SphK1/FAK-mediated carcinogenesis, metastasis and increased cell motility, and their higher serum levels may serve as prognostic markers for tumor progression and metastasis in patients suffering from colorectal cancer." (PMID 32456134, 2020). "Interestingly, a recent clinical study reported that in patients with SphK1-positive colorectal cancer, S1P formation is correlated to enhanced cell migration and metastasis with a worse prognosis with respect to patients that are affected by SphK1-negative cancer." (PMID 31703256, 2019).
colorectal cancer (continued). "In addition, the Sphk1 inhibitor N′-(3-(benzyloxy) benzylidene)-3,4,5-trihydroxybenzohydrazide also decreased expression of interleukin IL-6 and cyclooxygenase-2 (COX-2) and significantly inhibited ulcerative colitis—a precancerous lesion of colorectal cancer—in a DSS-induced rodent model." (PMID 28991193, 2017).